HMGB1 (high mobility group box 1)
Diseases named in the same sentence as HMGB1 in open-access papers (continued):
Sharing a sentence is not in itself a finding about the gene and the disease.
Sepsis (continued). "Furthermore, RA reduced CLP-induced HMGB1 release and sepsis-related mortality." (PMID 32629817, 2020). "Research revealed that HMGB1 could inhibit NADPH oxidase activation, leading to a deficiency in oxidative burst and dysfunction of neutrophil-dependent bacterial killing mechanisms in an experimental sepsis model and in patients surviving septic shock." (PMID 33552058, 2020). "Therefore, the HMGB1/IL-17A axis may play a key role in myocardial dysfunction resulted from sepsis." (PMID 32849528, 2020). "In addition, injection of GW4869, exosome inhibitor, or knockdown of Rab27, a GTPase required for exosome release, into LPS-challenged mice resulted in significant lower levels of HMGB1 in the plasma, suggesting the importance of exosomes as couriers of HMGB1 during sepsis." (PMID 33013905, 2020). "Therefore, the modulation of the release of HMGB1 from endothelial cells and the regulation of released HMGB1-mediated signal pathways in endothelial cells may provide a novel means of treating acute inflammatory conditions, especially in sepsis." (PMID 32498020, 2020). "Therefore, in this study, we investigated the roles of sesamin in regulating the development of sepsis via the HMGB1/TLR4/IL-33 signalling pathway by examining its impacts on the production of pro-inflammatory cytokines and the expression of IL-33, HMGB1, TLR4, ZO-1, and occludin." (PMID 32893702, 2020). "Clinically, patients with sepsis have elevated serum levels of HMGB1, and these levels are associated with the severity of organ damage and death, suggesting that HMGB1-targeting strategies might be a viable option for clinical trials of sepsis and perhaps other inflammatory diseases." (PMID 33603756, 2020). "Moreover, multiple studies on animal models of sepsis found that suppression HMGB1/TLR4/NF-κB signaling pathway could attenuate inflammation response and ultimately reduce the damage of vital organs as well." (PMID 33552058, 2020). "Thus, current study elucidates protective effects of HRG on vascular endothelial cells through inhibition of HMGB1-mediated pathways may contribute to the therapeutic effects of HRG on severe sepsis." (PMID 32498020, 2020). "Understanding the contributions of HMGB1 to the pathogenesis of sepsis may facilitate development of potentially effective therapeutic strategies to shorten the course of the disease as much as possible, and to improve the prognosis and survival rate of sepsis patients." (PMID 33552058, 2020). "In the setting of sepsis involving both an uncontrolled system inflammatory response and refractory immunosuppression, the neutralization of central HMGB1 activity might be an effective target for breaking the vicious cycle of disturbed neuromodulation caused by brain injury." (PMID 30881224, 2019). "This study also showed that paeonol and miR-339-5p may be promising therapeutic agents for the treatment of various inflammatory diseases such as Parkinson’s disease, organ failure, cancer, and especially sepsis, while HMGB1 and IKK-β may be promising therapeutic targets." (PMID 31852965, 2019). "Thus, there may be a window of opportunity following sepsis during which administration of anti-HMGB1 antibodies or other HMGB1 nullifying agents may prevent or even reverse neural impairment." (PMID 31892321, 2019). "Moreover, the increased mortality rate was paralleled by increased serum levels of HMGB1, supporting the hypothesis that mortality results from sepsis due to the severe mucosal damage." (PMID 29791477, 2018). "Furthermore, a small-molecule inhibitor of HMGB1, P5779, shown previously to protect mice against hepatic ischemia/reperfusion injury and sepsis, also significantly protected mice against influenza-induced lethality and lowered clinical scores, comparable to Eritoran treatment." (PMID 29535197, 2018).
Sepsis (continued). "Comparing with early-acting role of TNF-α and IL-1, HMGB1 was identified as a late-acting cytokine to influence the progression of sepsis, so we speculated that anti-HMGB1 therapeutics would become an effective approach to treat inflammation-related autoimmune disease." (PMID 30410469, 2018). "Moreover, therapies targeting HMGB1, but also other DAMPs, might be adopted from the oncology and sepsis fields, and applied for use in surgery and/or chemotherapy-induced immune suppression." (PMID 29675023, 2018). "However, extracellular HMGB1 is now recognized as a critical late mediator of sepsis." (PMID 29535197, 2018). "Though the released HMGB1 might facilitate tissue repair during sterile injury, excessive accumulation of extracellular HMGB1 in tissue or circulation contributes importantly to the pathogenesis of many inflammatory or autoimmune diseases, such as sepsis and colitis." (PMID 30134814, 2018). "Moreover, we suggested that miR-181a-5p may play a role in regulating DC responses to HMGB1 and serve as evidence indicating that novel therapies targeting miRNAs may be useful for treating immune dysfunction in the setting of sepsis." (PMID 28947753, 2017). "In the present study, the activation of NF-κB coupled with proinflammatory cytokines secretion and the increase of HMGB1 protein expression/nucleocytoplasmic translocation were observed in the lungs during sepsis-induced acute lung injury, which could be effectively reduced by salidroside treatment." (PMID 28931916, 2017). "Therefore, HMGB1 might be a promising target for preventing the occurrence and the progression of brain dysfunction, which can be addressed right after the onset of sepsis through intracerebroventricular administration of antagonists." (PMID 29190939, 2017). "Therefore, inhibiting HMGB1 translocation and release might protect against sepsis-induced acute lung injury and may offer a wider therapeutic window for sepsis." (PMID 28931916, 2017). "In addition, salicylic acid (SA) could bind to HMGB1 and suppress its proinflammatory activities during sepsis." (PMID 28039939, 2017). "Therefore, targeting HMGB1 may be an important strategy for the treatment of sepsis and other inflammatory diseases." (PMID 29333216, 2017). "However, the role of HMGB1 in sepsis induced brain dysfunction remains intricate." (PMID 29190939, 2017). "There is a C5aR2-dependent upregulation of HMGB1 in sepsis both in vivo and in vitro, while in the context of cerebral malaria induced by Plasmodium falciparum it is C5aR1, but not C5aR2, that causes the elevated plasma HMGB1." (PMID 28706957, 2017). "Truncation of HMGB1 into individual structural domains revealed that HMGB1 A box, a DNA‐binding motif, could specifically antagonize the activity of HMGB1 and rescue mice from lethal sepsis." (PMID 28039939, 2017). "A series of basic studies have shown that HMGB1 is closely related to the inflammatory response, which mediates the release of multiple inflammatory mediators and proinflammatory factors and is therefore considered to be a potential therapeutic target in the sepsis study model." (PMID 29073894, 2017). "Targeting HMGB1 may be an ideal therapy for sepsis and several studies have shown positive results." (PMID 28484719, 2017). "DOE and its active components may therefore also exert its action on the cellular response against inflammation by regulating LPS-induced release of HMGB1, which is a late-phase proinflammatory cytokine that plays an important role in the pathogenesis of sepsis." (PMID 28403838, 2017). "Thus, HMGB1 is an important factor that not only directly contributes to multiple organ injuries, but also mediates gut BT to trigger/induce systemic inflammation/sepsis, the latter can lead to MODS." (PMID 27980458, 2016). "In addition, HMGB1 is thought to be alate mediator of sepsis." (PMID 26648090, 2016). "However, extracellular HMGB1 serves as a proinflammatory cytokine and is a late mediator of sepsis." (PMID 27553758, 2016).
Sepsis (continued). "Interestingly, HMGB1 inhibitors and neutralizing antibodies significantly increase survival in septic patients, suggesting that HMGB1 might be a therapeutic target for sepsis." (PMID 27716835, 2016). "Moreover, the protective effects of XBJ in the development of CLP-induced lung injury during sepsis may be relevant to the modulation of cytokines-mediated inflammation in the lung via downregulation of HMGB1 and RAGE expressions." (PMID 25821501, 2015). "APAP overdose induces massive hepatocyte necrosis and necrotic tissue passively releases HMGB1, a ubiquitous nuclear protein secreted by immunocompetent cells, including monocytes, macrophages and neutrophils, is an important late inflammatory mediator in sepsis." (PMID 24708589, 2014). "Therefore, for the treatment of sepsis and other diseases, inhibiting HMGB1active release and/or blocking HMGB1 pro-inflammatory activities could be more effective ways to help patients achieve better therapeutic outcomes." (PMID 24603876, 2014). "In an experimental rat model of sepsis caused by cecal ligation and puncture (CLP), Gu-4 administration prominently attenuated lung injury and improved the survival of the septic animals, which was positively correlated with the decrease of the serum HMGB1 level." (PMID 24603876, 2014). "In addition, HMGB-1 has been identified as late cytokine mediator of endotoxaemia and sepsis." (PMID 24188108, 2013). "Thus, the therapeutic window for anti-HMGB1 therapies is significantly wider than that of TNF-α targeted interventions, and it may now be possible to develop inhibitors of HMGB1 for the treatment of sepsis." (PMID 24371375, 2013). "Studies in experimental models of sepsis, a life threatening syndrome of systemic inflammation with pathophysiological features resembling SM (including vascular permeability, and multi-organ dysfunction), suggest that HMGB1 is involved in mediating sepsis-related pathology." (PMID 23506269, 2013). "Interestingly analysis of circulating HMGB1 from sepsis survivors by mass spectroscopy demonstrated a stepwise increase of reduced form of HMGB1 (with known chemo-attractant properties) during the first 3 weeks, followed by disulphide form (with known inflammatory properties) 4-8 weeks after CLP." (PMID 23808943, 2013). "Furthermore, our finding that exogenous administration of C23–45 rHMGB1 in healthy mice is sufficient to cause expansion and increased cytokine response of splenocytes suggests that elevation of HMGB1 can mediate the long-lasting changes in immunophenotype observed in murine sepsis survivors." (PMID 23808943, 2013). "At the same time, targeting HMGB1 with either antibodies or specific antagonists has been demonstrated to blunt inflammatory response and confer protective effects in animal models, including lethal endotoxemia or sepsis, collagen-induced arthritis, and ischemia-reperfusion induced tissue injury." (PMID 23359306, 2013). "Based on the hypothesis that HMGB1 released during infection contributes to disease pathogenesis, the therapeutic efficacy of an HMGB1 neutralizing monoclonal antibody (2G7) was investigated in ECM-susceptible mice, at a dose previously shown to confer protection in experimental sepsis models." (PMID 23506269, 2013). "The underlying mechanisms by which MBC extract conferred protection against lethal sepsis are complex, but may be attributable to the inhibition of endotoxin-induced release of HMGB1, IL-6, and several chemokines (including MCP-2, MCP-3, RANTES, GRO, and I-309)." (PMID 23193422, 2012). "Thus, inhibition of HMGB1 release via HO-1 treatment may represent a potential application for therapeutic intervention against sepsis." (PMID 22518295, 2012). "Therefore, HMGB-1 is a necessary and sufficient mediator in severe sepsis because independent strategies that inhibit its inflammatory potential prevent multiple organ failure and rescue mice from established sepsis." (PMID 22075574, 2011).
Sepsis (continued). "Whereas a blockade of extracellular HMGB1 might represent a suitable therapeutic target for the treatment of sepsis, the development of the appropriate cell-mediated immunity, which is associated with a Th1 type immune response, is essential for successful immunization." (PMID 21915243, 2011). "Targeting of HMGB-1 via, for example, specific neutralising antibodies seems therefore appealing as it was shown in animal models that this may protect rodents from lethal sepsis." (PMID 20652004, 2010). "Furthermore, our findings support the view that increased levels of HMGB1 constitute an early phenomenon in traumatic insult, in contrast to the evidence reported for human sepsis as well as for experimental models of endotoxemia, in which HMGB1 is considered a late mediator." (PMID 21044333, 2010). "Other receptors may be involved in sustaining this inflammatory challenge; for example, HMGB-1 has been shown to activate TLRs and receptor for advanced glycation end-products and it has been reported as a key late pro-inflammatory mediator in sepsis, with considerable pathological potential." (PMID 20470406, 2010). "HMGB1 has been shown to be a potent mediator of late septic shock that results from endotoxin stimulation of macrophages and there are indications that it may be a valuable therapeutic target in the treatment of sepsis." (PMID 19609357, 2009). "There is experimental evidence that HMGB1 may be an early mediator of sterile inflammation induced by hypoxia and ischemia-reperfusion, although previous experimental and clinical studies have demonstrated its role as a late mediator of inflammation in sepsis." (PMID 19887013, 2009). "Furthermore, neutralizing antibodies directed atHMGB-1 rescued mice from lethal endotoxemia even when administered 24 hoursafter sepsis initiation.For these reasons, HMGB-1 is viewed as an attractive therapeutic target for various inflammatorydisorders including endotoxic shock." (PMID 19009026, 2008). "However, unlike monocyte-driven sepsis caused by endotoxin, translocation and secretion of HMGB-1 mediated by TSST-1 was dependent on the presence of both activated T cells and monocytes." (PMID 19009026, 2008). "Inflammatory mediators were markedly increased in sepsis (TNF-α, IL-6, HMGB1, TLR-4, and NF-κB; all p < 0.001 vs. Control) and significantly downregulated by pioglitazone (p < 0.01, p < 0.001, p < 0.001, p < 0.01, p < 0.01 vs. CLP + Saline, respectively)." (PMID 41899201, 2026). "Quercetin, the main active ingredient in Huanglian Jiedu decoction, can reduce ROS levels in the lung tissue of septic rats, decrease HMGB1 expression, and inhibit the activation of the PI3K/Akt pathway, thereby protecting against sepsis-induced lung injury." (PMID 41041277, 2025). "Similarly, serum HMGB1 levels in sepsis patients have been reported to be higher in non-survivors compared to survivors, suggesting that HMGB1 could be associated with severe disease progression." (PMID 39849347, 2025). "Extracellular HMGB1 binds to TLR4 and receptors for advanced glycation end-products (RAGE) to exacerbate inflammation in sepsis." (PMID 40421030, 2025). "Sepsis progression involves a biphasic inflammatory response, with early mediators like TNF-α followed by late mediators including HMGB1, which provides a crucial therapeutic window for intervention." (PMID 41155644, 2025). "HMGB1 has been proposed as a useful molecule to differentiate patients with SIRS and sepsis in pathologies such as secondary peritonitis." (PMID 40868835, 2025). "An animal study reported reduced serum interleukin-6 (IL-6), high mobility group protein B1 (HMGB)-1, and tumor necrosis factor-α(TNF-α) levels but increased interleukin-10 (IL-10) levels in the group given esmolol compared with the sepsis group." (PMID 40522976, 2025).
Sepsis (continued). "Several major DAMPs, such as eCIRP, HMGB1, histones, ATP, IL-33, eNAMPT, and RIPK3 are elevated during sepsis, hemorrhagic shock, I/R, acute pancreatitis, traumatic injury, ARDS, and pediatric diseases." (PMID 40406124, 2025). "Since eCIRP, HMGB1, and histone H3 are the major DAMPs that promote inflammation via TLR4 in sepsis, we selected them as targets to be cleared from circulation." (PMID 40421030, 2025). "For example, during sepsis, macrophages can absorb extracellular lactate through the MCT to promote high mobility group box-1 (HMGB1) lactylation, thereby increasing endothelial permeability and inducing endothelial barrier dysfunction." (PMID 40584617, 2025). "Sepsis can disrupt the BBB, resulting in an elevation of inflammatory factors within the brain, such as interleukin-6 (IL-6) and high mobility group box 1 (HMGB1)." (PMID 41357214, 2025). "Most importantly, CDDO-Im also decreased HMGB1 protein levels in the serum and BALF after sepsis exposure." (PMID 40599023, 2025). "In conclusion, we demonstrated that CDDO-Im alleviates sepsis-related ARDS through the activation of PINK1/Parkin-mediated mitophagy to inhibit AM pyroptosis and HMGB1 release bothin vivo andin vitro via the Nrf2 pathway." (PMID 40599023, 2025). "HMGB1 also plays a crucial role in aseptic inflammation by activating the NLRP3 inflammasome, inducing IL-1β secretion and sepsis, and recruiting neutrophils and eosinophils, resulting in inflammatory infiltration and tissue damage." (PMID 40688353, 2025). "Our study addresses this gap by simultaneously evaluating sTREM-1, HMGB1, sCD14-ST, IL-10, vitamin D, and sHLA-G in patients with SIRS and sepsis." (PMID 41153764, 2025). "Simultaneous blockade of the HMGB1—TLR4 axis (e.g., via neutralizing antibodies) and the NLRP3 inflammasome (e.g., using MCC950) can decrease the secretion of IL—1β in experimental sepsis models." (PMID 40877572, 2025). "During sepsis, macrophages enhance the lactylation of the high mobility group box-1 (HMGB1) via p300/CBP, which damages endothelial cells and promotes the progression of sepsis." (PMID 40421024, 2025). "In vivo analyses reveal a physical interaction between SIRT1 and HMGB1 within the nucleus, with SIRT1 modulating the acetylation of HMGB1 to combat sepsis-induced liver damage." (PMID 38690282, 2024). "Lactate can induce HMGB1 lactylation through a p300/CBP-dependent mechanism, thereby exacerbating the progression of sepsis." (PMID 39850900, 2024). "CGK012 effectively mitigated excessive permeability and suppressed HMGB1 release, resulting in improved vascular stability, decreased mortality, and enhanced histological conditions in the mouse model of CLP-induced sepsis." (PMID 38474222, 2024). "Instead, their results indicated that TIM-3 exhibits a relatively strong binding affinity for HMGB1, suggesting its potential as a receptor for HMGB1 in TIM-3+ CD4+ T cells during sepsis." (PMID 38576606, 2024). "High mobility group box 1 (HMGB1), a protein with important functions, has been recognized as a potential therapeutic target for the treatment of sepsis." (PMID 38474222, 2024). "Lactic acid promoted the Kla of HMGB1 through a p300/CBP-dependent mechanism, and the balance of Kla and Kac on HMGB1 in macrophages promoted the development of polymicrobial sepsis." (PMID 38862432, 2024). "In animal models of lethal sepsis induced by cecal ligation and puncture (CLP), circulating HMGB1 levels peaked between 24-36 hours." (PMID 39763679, 2024). "Key substances include high mobility group box 1 (HMGB1) and heat shock proteins (HSPs), which are DAMPs released from cells during sepsis." (PMID 39056754, 2024). "High-mobility group box 1 (HMGB1) is a lethal cytokine in the cecal ligation and puncture-induced sepsis model." (PMID 39206262, 2024).